TSHR (thyroid stimulating hormone receptor)
Diseases named in the same sentence as TSHR in open-access papers (continued):
Sharing a sentence is not in itself a finding about the gene and the disease.
Graves disease (continued). "Some researchers speculate that TSHR activation by TSAb affects body fat composition in Graves’ disease patients; however, the final effect depends on thyroid status." (PMID 34574358, 2021). "Furthermore, a phase I trial of apitopes in Graves’ disease, with epitopes from the TSHR [51•], noted a reduction in both thyroid hormone secretion and anti-TSHR antibodies in 7/10 patients [19••]." (PMID 33878516, 2021). "Moreover, the study explores the potential of human organoids for modeling autoimmune disease, the anti-TSH receptor (TSHR) antibody-driven Graves’ hyperthyroidism." (PMID 34916298, 2021). "As studied particularly in Graves’ Disease, neutral, stimulating, and blocking thyrotropin receptor (TSHR) abs have been described, which may compete for receptor binding with overlapping epitopes." (PMID 33384684, 2020). "The development of animal models for Graves’ disease were accelerated with the sequencing of the TSHR and consequently the availability of recombinant TSHR DNA, which made it amenable to prepare substantial quantities of recombinant TSHR protein or synthetic peptides for active immunization." (PMID 32399893, 2020). "Almost two decades later in 1974, pivotal studies by Smith and Hall showed that these autoantibodies in sera of patients with Graves’ disease target the TSH receptor (TSHR) and stimulation of the TSHR by autoantibodies is responsible for thyroid overactivity in Graves’ disease." (PMID 32472423, 2020). "This is the first step in development of K1-70TM as a novel drug for improving the management of patients with Graves’ disease, patients with Graves’ ophthalmopathy, patients with thyroid cancer and other patients who would benefit from control of their TSHR activity." (PMID 32257067, 2019). "The experimentally estimated serum TRAb concentrations in patients with Graves’ disease ranged from 50 to 500 μg/L (TRAb range 1.5–110 U/L) while in patients with autoimmune hypothyroidism with TSHR blocking autoantibodies ranged from 1.7 to 27 mg/L (TRAb range 134–1290 U/L)." (PMID 32257067, 2019). "The thyroid-stimulating hormone receptor (TSHR) is the major autoantigen in Graves’ disease, but TSHR antibodies may occur also in some patients with Hashimoto’s disease." (PMID 29931474, 2018). "The presence of such TSHR antibodies suggests that they may play an active role in the immune repertoire marshaled against the TSHR and may influence the Graves' disease phenotype." (PMID 30666231, 2018). "Graves’ disease (GD) is characterized by thyrotoxicosis and goiter and arises through circulating autoantibodies that bind to, and stimulate, the thyroid hormone receptor (TSHR)." (PMID 30219088, 2018). "Graves’ disease is characterized by thyrotoxicosis and goiter and arises through circulating autoantibodies that bind to, and stimulate, the thyroid hormone receptor (TSHR)." (PMID 30219088, 2018). "Autoantibodies to the TSHR found in patients with Graves' disease may be stimulating, blocking, or neutral based on their modulation of cyclic AMP signaling." (PMID 30666231, 2018). "Single-nucleotide polymorphisms (SNPs) in TSHR have been specifically associated with Graves’ disease (but not HT) in the Caucasian population." (PMID 29931474, 2018). "In pregnancy, as in not pregnant state, thyroid-stimulating hormone (TSH) receptor (TSHR) antibodies (TRAbs) are the pathogenetic hallmark of Graves’ disease." (PMID 28713331, 2017). "Additionally, 30% of murine MHC class II knockout HLA-DR3 transgenic NOD mice vaccinated with TSHR DNA showed TSAb induction and Graves’ hyperthyroidism." (PMID 27895620, 2016). "In Graves’ disease, immune tolerance toward self-antigen TSHR is obviously dysfunctional, such that, from a classical point of view, endogenous TSHR processed in the cytosol of thyrocytes gives rise to peptides for human leukocyte antigen (HLA) class I presentation to CD8+ T cells." (PMID 27895620, 2016).
Graves disease (continued). "TSHR autoantibody was first discovered in a search for thyroid-stimulating activity in the serum of Graves’ disease patients, which was known to stimulate radioiodine release from pre-labeled guinea pig thyroids for a much longer time period than did pituitary TSH treatment." (PMID 27895620, 2016). "Moreover, evidence suggests that only TSHR is the primary autoantigen of Graves’ disease, whereas immune responses to other thyroid antigens (e.g., Tg and TPO) simply reflect concomitant thyroiditis." (PMID 27895620, 2016). "The TSHR is also a target autoantigen in autoimmune thyroid disease, especially Graves’ disease." (PMID 26858688, 2016). "This study hypothesized that the different actions of thyroid-stimulating hormone receptor (TSHR) antibodies, both stimulating and blocking activities in Graves’ disease patients might oppositely impact bone turnover." (PMID 26650844, 2015). "Clinical studies with TSHR primarily focus on Grave’s disease." (PMID 24959420, 2014). "Graves' disease (GD) is an organ-specific autoimmune disease characterized by the production of agonistic auto antibodies against the thyroid-stimulating hormone receptor (TSHR), which mimic the stimulatory effects of TSH, leading to hyperthyroidism and diffuse hyperplasia of the thyroid gland." (PMID 25226272, 2014). "Likewise, thyroid autoantibodies bind and stimulate the thyroid stimulating hormone receptor (TSHR), which causes hyperthyroidism in the autoimmune process of Grave’s disease." (PMID 23516437, 2013). "Hence, women with a suppressed TSH and all those with a history of Graves' disease need to be screened carefully in the post partum for the presence of TSHR-Abs." (PMID 23691429, 2013). "Graves’ disease (GD) is one of the most common autoimmune diseases (AIDs) and is characterized by the production of autoantibodies that bind and stimulate the thyroid-stimulating hormone receptor (TSHR), resulting in hyperthyroidism and diffuse enlargement of the thyroid gland." (PMID 24386393, 2013). "In the EAGD model, which uses cDNA immunization with human TSHR to induce Graves' disease, a significant T-cell and antibody response is observed to human TSHR, and the antibodies, through cross-reaction with the mouse TSHR, stimulate the mouse TSHR causing thyrotoxicosis." (PMID 21559421, 2011). "Thesedifferences are likely to be reflective of TSHR-Abs seen in Graves' disease." (PMID 16050145, 2005). "Unlike traditional scFvs, TSHR is a G protein-coupled receptor with four extracellular domains that specifically bind pathogenic autoantibodies to its N-terminal (21–413 amino acids), offering a novel approach for treating Graves’ disease." (PMID 41357209, 2025). "Graves’ disease, which is characterized by thyrotoxicosis, is an autoimmune thyroid disease in which lymphocytic infiltration of the thyroid gland and production of antibodies to the thyrotropin receptor (TSHr antibodies), results in overproduction of thyroid hormone." (PMID 37477245, 2023). "The effect of stimulatory anti-TSHR antibodies is an increase in thyroid hormone production leading to autoimmune hyperthyroidism (Graves’ disease) as well as Graves’ ophthalmopathy, and more than half of the patients with Graves’ disease are positive for such antibodies." (PMID 37047169, 2023). "Therefore, the effect of AT1R-AAs may be related to a type II hypersensitivity response, similar to autobodies of thyroid-stimulating hormone receptor (TSHR) that can overactivate TSHR in Graves’ disease." (PMID 37330563, 2023). "It is unclear that whether TSHR function and thyroid disorders, such as; Graves' disease (GD) are relatively associated or not, and that TSH screening has facilitated their diagnosis." (PMID 36130976, 2022).
Graves disease (continued). "This is in contrast to autoimmune hyperthyroidism, a disease in which maternal activating thyroid-stimulating hormone receptor antibodies may lead to thyrotoxicosis in the baby or autoantibodies in mothers with systemic lupus erythematosus may lead to bradycardia or neonatal lupus in the newborn." (PMID 34570215, 2022). "Once TSH could be radiolabeled without losing its biological activity, it became possible to rapidly detect such stimulating activity in sera from patients with Graves’ disease since the antibody had been shown to be an immunoglobulin (IgG) which would compete with TSH for binding to the TSHR." (PMID 35909553, 2022). "In addition, blocking TSHR activity with K1-70 may benefit patients with thyroid cancer and Graves’ disease." (PMID 32472423, 2020). "Targeting of the TSHR with K1-70TM may provide new therapeutic strategies for the management of patients with Graves’ disease, patients with Graves’ ophthalmopathy, patients with thyroid cancer and other patients who would benefit from controlling TSHR activity." (PMID 32257067, 2019). "Graves’ disease is an organ-specific antibody-mediated autoimmune disease, governed by both genetic predisposition and environmental factors, in which thyroid-stimulating antibodies (TSAb) mimic the function of thyroid-stimulating hormone (TSH) to activate the thyrotropin receptor (TSHR)." (PMID 29801507, 2018). "In addition to the well-known effects of TSHR antibodies on fibroblasts in Graves’ disease (GD), studies speculate on a role of anti-thyroid antibodies in cancer." (PMID 28536577, 2017). "Autosomal dominant non-autoimmune hyperthyroidism may be caused by germ-line TSHR mutations, and de novo mutations may lead to sporadic non-autoimmune hyperthyroidism." (PMID 28117293, 2017). "TSHR mutations are defined in several diseases like familial gestational hyperthyroidism, autonomous toxic adenomas, hereditary or sporadic toxic thyroid hyperplasia, familial non-autoimmune hyperthyroidism, Graves’ disease and autoimmune hypothyroidism." (PMID 28117293, 2017). "In mice induced to develop Graves’ disease by immunization with an adenovirus encoding the TSHR A-subunit gene, pretreatment with a non-pathogenic (or “inactive”) form of TSHR A-subunit protein attenuated hyperthyroidism by diverting pathogenic TSHR antibodies to a non-functional variety." (PMID 29326719, 2017). "The desired models that reflect the actual pathogenesis of Graves’ disease would have spontaneous disease onset without any artificial immunization of the causative antigen, i.e., TSHR, solely by modulating other factors that are suspected to trigger and/or accelerate autoimmune reactions." (PMID 27895620, 2016). "Indeed, a comparative study performed using purified IgGs from 58 patients with Graves’ disease showed that a bioassay based on Chinese hamster ovary (CHO) cells transfected with rh-TSHR had a higher sensitivity than the FRTL-5 bioassay (93 vs. 75.8%, respectively)." (PMID 27504107, 2016). "Moreover, after reaching the remission of Graves’ disease, TSHR antibodies could exist persistently in their sera, especially when treated with radioactive iodine." (PMID 26650844, 2015). "Graves’ disease (GD) is an organ-specific autoimmune disorder characterized by the loss of immunological tolerance, which is pivotal to the appearance of pathogenic autoantibodies against thyroid peroxidase (TPO), thyroglobulin (Tg), and the TSH receptor (TSHR)." (PMID 23189166, 2012). "However, as we mentiond before, Graves’ disease (GD) is an organ-specific autoimmune disorder characterized by the appearance of pathogenic autoantibodies against thyroid peroxidase (TPO), thyroglobulin (Tg), and the TSH receptor (TSHR)." (PMID 23189166, 2012). "Therefore, this strain immunized with A-subunit-adenovirus that generates only functional TSHR antibodies may provide an improved model for studies of induced Graves' disease." (PMID 21738647, 2011).
Graves disease (continued). "In AIH, it regulates Treg cell function through the PI3K-Akt pathway, and in Graves' disease, GRK2 activity is increased by TSH receptor (TSHR)–specific autoantibodies, exacerbating the autoimmune response." (PMID 40224487, 2025). "Graves’ disease is an autoimmune disorder characterized by the production of TSI, which activates the TSHR and leads to hyperthyroidism." (PMID 41415293, 2025). "An earlier report indicated that SEA suppresses the production of Th1-type anti-TSHR IgG2a autoantibodies and IFN-γ during Graves hyperthyroidism, which decreases the severity of the disease." (PMID 39481080, 2024). "Overstimulation of the TSHR induces hyperthyroidism and thyroid eye disease (TED) as the most common extra thyroidal manifestation of Graves’ disease." (PMID 37810891, 2023). "Moreover, Graves’ disease is considered as the consequence of a breakdown in TSHR tolerance, and selected cleavage TSHR antibody could produce a robust effect on the MAPK/PI3K-AKT/mTOR/S6K signaling cascades, the maintenance of which determined the thyroid cell fate of death." (PMID 35846879, 2022). "Historical models of Graves’ disease and TAO have focused almost entirely on autoimmune reactivity directed against the thyrotropin receptor (TSHR)." (PMID 33673340, 2021). "Little is known regarding the role of the microbiome in Graves’ disease (GD), which is characterized by thyroid-stimulating antibodies (TSAbs) binding to the thyrotropin (TSH) receptor (TSHR) resulting in thyroid hyperplasia and hyperthyroidism." (PMID 33593429, 2021). "The TSHR is also detected and increased in OAT in GO, and is an essential cellular target both for GO and Graves disease." (PMID 34473251, 2021). "The TSHR-mediated growth of thyroid was initially observed in TSH-secreting pituitary adenoma and Graves’ disease." (PMID 32698392, 2020). "The functionality of TSHR, driving cAMP accumulation in response to the stimulation of bovine TSH (bTSH) and immunoglobulins isolated from patients with Graves’ disease, was also demonstrated in this study." (PMID 32698392, 2020). "The thyroid-stimulating hormone (TSH) receptor (TSHR) is a class A G protein-coupled receptor (GPCR) and is the target autoantigen in Graves’ disease." (PMID 27921237, 2017). "Graves’ diseases (GD) is an organ-specific AID, in which the major antigenic target is the thyroid-stimulating hormone receptor (TSHR)." (PMID 29190882, 2017). "We hypothesize that TSHR activation [TSHR*, elevated thyroid-stimulating hormone, thyroid-stimulating antibodies (TSAB), or activating mutation] influences MSC differentiation, which contributes to body composition changes seen in hypothyroidism or Graves’ disease (GD)." (PMID 28469599, 2017). "In contrast, potent antagonists against the TSHR would be useful for the treatment of hyperthyroid Graves’ disease by blocking thyroid-stimulating antibodies without the risk of anti-thyroid drug side effects and may also have a role in treating Graves’ eye disease." (PMID 26858688, 2016). "Graves’ disease (GD) is an organ-specific autoimmune disease, and thyrotropin (TSH) receptor (TSHR) is a major autoantigen in this condition." (PMID 27602020, 2016). "Given that TSHR signaling has a functional role in the bone metabolism of hyperthyroidism, we hypothesized that the different actions of TSHR antibodies, both stimulating and blocking activities in Graves’ disease patients, might oppositely impact bone metabolism." (PMID 26650844, 2015). "TSHR-Abs were initially described by Adams and Purvis in the 1950s as a long acting thyroid stimulator (LATS) in the sera of patients with severe Grave's disease." (PMID 23691429, 2013). "A similar mechanism would be expected to play a role in MHC class II binding for peptides of the thyrotropin receptor (TSHR), the autoantigen in Graves' disease." (PMID 21738647, 2011).
Graves disease (continued). "They developed a type of Graves' Disease (GD) after being injected with fibroblasts coexpressing MHC class II and the TSH receptor (TSHR)." (PMID 15762980, 2005). "The present study demonstrates that oral administration of NES-428 significantly ameliorates hyperthyroidism induced by TSHR overexpression in a murine hyperthyroidism model, supporting the potential of NES-428 as a preventive agent for autoimmune thyroid disorders such as Graves’ disease." (PMID 41010493, 2025). "The full extent of the anti-TSHR immune reactions induced by SEA on Graves hyperthyroidism is unclear, as it has not been studied extensively." (PMID 39481080, 2024). "Recently, cepharanthine has been revealed to block the binding of the TSH receptor peptide (TSHR.132) to HLA- DRβ1-Arg74 and, thus, to inhibit T-cell activation and cytokine response in a humanized, HLA-DR3 expressing, mouse model of Graves’ disease." (PMID 38791433, 2024). "The thyroid stimulating hormone receptor (TSHR) is crucial in thyroid hormone production in humans, and dysregulation in TSHR activation can lead to adverse health effects such as hypothyroidism and Graves' disease." (PMID 37546222, 2023). "In the late TSHR immunized group 4 mice did not develop an autoimmune hyperthyroidism or the thyroid dysfunction was declining to euthyroid conditions." (PMID 37435490, 2023). "Overall, hFMT and Lab4 increased the incidence and severity of autoimmune hyperthyroidism whereas vancomycin treatment led to mild or no disease compared with TSHR-ddH2O." (PMID 33593429, 2021). "By contrast, thyroid stimulating hormone receptor (TSHR) and lysine demethylase 6B (KDM6B), which are known primary antigens in autoimmune diseases, including Graves' disease and Hashimoto's disease and systemic sclerosis (SS also termed scleroderma) were highly expressed in asymptomatic males." (PMID 34965855, 2021). "Importantly, this is not an artificial in vitro phenomenon, since reduced TSHR expression was also demonstrated ex vivo by immunhistochemical analysis of thyroid tissue from patients with gain-of-function TSHR mutations compared with normal and Graves’ disease thyroid tissue." (PMID 32303903, 2020). "Since this receptor responds to TSH and stimulates the production of thyroid hormones, it was suggested earlier that in Graves disease (a condition of hyperthyroidism), the activation of TSHR is seen with low or no TSH28,29." (PMID 31439949, 2019). "In Graves’ disease (GD, hyperthyroidism), the main autoantigen (anti-TSHR antibody) activates TSHR without TSH and it is accompanied with high insulin concentration." (PMID 29386586, 2018). "In clinical, the glucose-stimulated insulin secretion (GSIS) is elevated in the patient with Grave’s disease (GD, hyperthyroidism), in which the anti-TSHR antibody activates TSHR without TSH5,6." (PMID 29386586, 2018). "Fifth, in experimental models, TSHR autoantibodies induced by conventional immunization using TSHR protein and a variety of adjuvants do not stimulate the thyroid gland and do not induce experimental Graves’ disease." (PMID 28620373, 2017). "Regulatory T cell depletion and administration of adjuvant in TSHR-transgenic mice did not reliably induce Graves’ disease." (PMID 27368808, 2017). "Graves’ disease (GD) is another main type of AITD, which is characterized by hyperthyroidism due to overproduction of thyroid hormones induced by specific auto-antibodies against thyrotropin receptor (TSHR)." (PMID 28225862, 2017). "Studies in patients with Graves’ disease have shown a variety of T cell epitopes in TSHR, with none appearing to be dominant." (PMID 28533776, 2017). "These assays included the current gold standard “third generation” immunoassay, which detects the ability of the respective mouse sera to inhibit the binding of the monoclonal Graves’ patient antibody M22 to the TSHR (RSR-Cobas Roche), which is most often used to identify Graves’ disease in humans." (PMID 27368808, 2017).